EGFR (epidermal growth factor receptor)
Diseases named in the same sentence as EGFR in open-access papers (continued):
Sharing a sentence is not in itself a finding about the gene and the disease.
tumor (continued). "Currently, two other phase 2 trials are ongoing to evaluate the efficacy of everolimus in patients with refractory, recurrent, and locally advanced HNSCC and to study the correlation of everolimus treatment with tumor- and patient-associated markers of the EGFR-mTOR pathway." (PMID 28108737, 2017). "This study indicates that EGFR mutation heterogeneity within the tumor is an additional variable that may predict response to TKIs: the percentage of mutated neoplastic cells has an impact on clinical response." (PMID 28520821, 2017). "Finally, CRIS-E aggregates KRAS-mutated, Paneth cell-like CIN tumours that are refractory to treatment with anti-EGFR antibodies." (PMID 28561063, 2017). "Using the TaqMan assay, a qualitative method, to detect EGFR mutations in plasma, it showed that median OS was significantly shorter in patients with both tumor and plasma L858R mutation (13.7 months) than in tumor-only L858R-positive patients (27.7 months) 19]." (PMID 28061461, 2017). "The T790M EGFR mutation rate was 63% in tumor biopsies, 50% in CTCs, and 50% in ctDNA." (PMID 29312651, 2017). "However, it is during the phases of tumor progression or relapse on treatment with TKI that LB is even more useful to detect resistance mutations in EGFR, in particular the T790M mutation that is sensitive to third generation TKI." (PMID 29125548, 2017). "99mTc-HYNIC-MPG had significantly higher accumulation in PC9 tumor cells when compared to H1975, H358 and H520 tumors cells, which may be due to the activating mutations (exon 19 deletion) in EGFR tyrosine kinase domain in PC9 cells." (PMID 28489575, 2017). "Third, the high-affinity EGFR model predicts that even minimal or residual activity of EGFR in human tumors treated with EGFR kinase inhibitors may be sufficient for tumor growth and may therefore underlie tumor resistance to such treatments." (PMID 29268862, 2017). "For some patients, biopsy samples might be the only tumor materials available for testing the EGFR mutation status and they are often composed of variable ratios of tumor to normal cells." (PMID 28336963, 2017). "The tumor genetic profile of the RAS/RAF pathway is needed before treatment with anti-EGFR agents; mutations in EGFR pathway genes have also been explored in relation to antiangiogenic molecules although further data are required prior to their integration into clinical practice." (PMID 28708103, 2017). "We next tested whether the multiplex assay can identify the specific mutation in genomic DNA from tumor cells harboring EGFR mutations." (PMID 28625519, 2017). "All EGFR L858R mutations detected in tumor tissues were found in peripheral blood (100%)." (PMID 28382702, 2017). "EGFR overexpression or activating mutation may promote tumor growth by increasing cell proliferation, motility, invasive capacity or by evading apoptosis, which were thus associated with poor prognosis." (PMID 28961023, 2017). "Also in this case, patients with EGFR or ALK genomic tumor mutations should have had disease progression on FDA-approved therapy for these aberrations prior to receiving atezolizumab." (PMID 28653990, 2017). "Moreover, objective response rates and progression-free survival were found to be similar in patients with EGFR mutations detected in their ctDNA and in those who were identified as EGFR mutation-positive in their tumor sample." (PMID 27980215, 2017). "Patient selection according to tumor mutations in the EGFR pathway might improve the overall response to combination therapy with Bmab as a first-line treatment for mCRC." (PMID 28068936, 2017).
tumor (continued). "Therefore, during the initiation of tumor formation, EGFR mutations decrease USP24 to increase the degradation of p300 and Bax, and thus repress cell apoptosis." (PMID 27991932, 2017). "Therefore, loss of sortilin promotes EGFR proliferative signaling and accelerates tumor growth in vivo." (PMID 29084952, 2017). "The PR patient had a tumor with an EGFR-activating mutation (L858R) and EGFR-TKI naïve setting." (PMID 28144730, 2017). "Intra-tumor heterogeneity appears to correlate to the EGFR mutations in NSCLC and may predict tumor responsiveness to TK inhibitors therapy." (PMID 28881771, 2017). "EGFRvIII is the most prevalent tumor-specific variant of EGFR." (PMID 28596941, 2017). "The detection rate of EGFR mutations in the tumor tissues in this study was 46.5%." (PMID 28052016, 2017). "Moreover, we demonstrated that levels of plasma EGFR mutations highly correlated with changes of tumor diameter as determined by radiographic imaging, or development of new lesions." (PMID 28969034, 2017). "Differences in SUVmax and serum tumor markers between different EGFR mutation statues." (PMID 28877268, 2017). "The majority of previous liquid biopsy studies in patients with EGFR mutations have primarily reported the feasibility of detecting resistance and sensitizing EGFR mutations and how much earlier tumor progression can be predicted using liquid biopsy than CT-scans." (PMID 28947971, 2017). "It was recently reported that tumor mutation burden in EGFR-TKI–resistant EGFR-mutant NSCLCs might be an important predictive indicator for PD1 inhibitor immunotherapy." (PMID 29296194, 2017). "Tumours with weakly detectable T3‐T4 increases in pEGFRm also showed modest HER2m increases (p = 0.027) and Spearman's analysis revealed direct associations at T4 between EGFR activity and pER (p = 0.006), Bcl‐2 (p = 0.055) and Ki67 (p = 0.047)." (PMID 26178788, 2016). "The efficacy in tumor targeting and gene knockdown of both EGFR and survivin was confirmed, and the profound reduction of tumor size and inhibition of tumor-associated blood vessels have been achieved, suggesting the efficacy of targeting on multiple proliferation pathways." (PMID 27456457, 2016). "However, aberrant EGFR signaling, sometimes caused by mutations at the EGFR TK domain, can lead to tumor growth and progression in the lung." (PMID 27610045, 2016). "We found that integrin overexpression could significantly (Student's t-test, P<0.0001) rescue the GSC tumour phenotypes associated with expressing a dominant-negative form of EGFR (EGFRDN), rlRNAi, zfh-1 and hopTum−l in somatic cells." (PMID 26792023, 2016). "However, previous comprehension of tumor heterogeneity was more limited to the proportion of cancer cells harboring EGFR-sensitive mutations." (PMID 27418143, 2016). "A portion of the tumor samples was analyzed previously for EGFR mutation studies." (PMID 27734950, 2016). "The detection rates for TKI-sensitizing or T790M mutations in plasma were not significantly related to sex, smoking status, EGFR mutation status at diagnosis, ECOG performance status, tumor stage, immediate prior treatment regimen, or type of EGFR-TKI first administered." (PMID 27542267, 2016). "Except for one tumor, tumors having both EGFR and KRAS mutations were moderately differentiated." (PMID 26992209, 2016). "Large phase III trials showed that afatinib performed well as first-line treatment in tumours bearing exon 19 deleted EGFR, but was unexpectedly ineffective on L858R mutant tumours or on gefitinib or erlotinib-pretreated tumours with a predominant T790M mutation." (PMID 27350784, 2016). "Since EGFRvIII mutation that is widely expressed in GBM and other neoplasms has a neoepitope resulting from an in-frame deletion of a part of the extracellular domain of EGFR, it might be an excellent target for CAR-engineered T cell therapy." (PMID 27833557, 2016).
tumor (continued). "While the proportion of T790M cells in circulation remains uncertain, a recent study examining TKI resistant tumor biopsies suggests that baseline allele frequency of T790M may impact on quality of 3rd generation EGFR TKI59." (PMID 26924553, 2016). "Large primary tumor size (≥5 cm) is significantly associated with wild-type EGFR." (PMID 27472739, 2016). "Direct aspirates of primary lung tumors contain different concentrations of tumor markers than serum tumor markers, and may correlate better with EGFR mutation than serum tumor markers." (PMID 26979333, 2016). "To find out whether human wt-EGFR transgene is mutated in the tumor, we isolated genomic DNA from mouse lung tumor nodules and checked mutational status in EGFR transgene through SURVEYOR mutation detection method." (PMID 26646697, 2016). "In addition, matched blood and tumor samples with information regarding the exact type of somatic EGFR mutations would help classify more specific subgroups and enable identification of stronger associations." (PMID 26906551, 2016). "It is important to note that despite the tumor entity, EGFR mutation could occur that leads to a resistance against TKIs, such as the mutation T790M that, in turn, is responsible for 50% of all EGFR-resistances against TKI." (PMID 26784235, 2016). "We did not observe any evidence for genetic heterogeneity in the surgical specimen, i.e., the ALK fusion event was present in all tumor cells which is consistent with the concept of mutual exclusivity with other main drivers, e.g., mutant EGFR, and the notion that ALK fusion are truncal mutations." (PMID 27863497, 2016). "The proliferation of tumor was associated with the levels of activated EGFR." (PMID 26883295, 2016). "Moreover, several serum tumor markers have been shown to be associated with EGFR mutation status and efficacy of EGFR-TKI treatment." (PMID 27072585, 2016). "The exposure to EGFR-TKIs may block the EGFR pathway and force the tumor cells to acquire abnormal mutations or activation of oncogenes and/or alternative signaling pathways, resulting in tumor cell proliferation." (PMID 27825114, 2016). "Tumor biopsy at this juncture showed the EGFR C797S mutation, in addition to the del 19 and T790M." (PMID 27448564, 2016). "Consequently, it will be essential to confirm the existence of T790M mutations in tumor resistant to EGFR-TKIs." (PMID 27478396, 2016). "In the adjuvant setting, the ongoing ADAURA trial (ADjuvant-AURA; NCT02511106) is a double-blind, randomized, placebo-controlled trial assessing the efficacy and safety of osimertinib vs. placebo in patients with EGFR-mutated stage IB–IIIA NSCLC following complete tumor resection." (PMID 28149837, 2016). "Twenty-six EGFR mutated patients from the ISEL study showed a tumor response rate of 37.5%." (PMID 27637087, 2016). "If successful, these agents could be moved forward into clinical trials for patients harboring tumors with specific tumor associated or tumor specific antigens, such as EGFR and EGFR variant III, respectively." (PMID 27783662, 2016). "When tumor proportion was below 20%, the EGFR mutation rate decreased." (PMID 26992209, 2016). "Interestingly, in our series 3/4 EGFR mutant patients with progressive disease after EGFR TKI treatment had coexisting mutations in KRAS or BRAF in the primary tumor, in two cases at an allelic frequency higher than EGFR mutations." (PMID 27448974, 2016). "Several studies have detected the coexistence of c-Met dysregulation and EGFR gene mutations in tumor tissues of NSCLC patients, and demonstrated that the PFS of patients with both EGFR mutations and c-Met gene amplification was significantly shorter than in patients with EGFR mutations alone." (PMID 27213587, 2016). "However, after a median duration of response of ~12 months, all patients develop tumor resistance, and in over half of these patients this is due to the emergence of the EGFR T790M resistance mutation." (PMID 28149837, 2016).
tumor (continued). "One could suggest that a patient’s plasma T790M status upon TKI failure, which mostly coexists with an EGFR activating mutation, is associated with increased tumor burden and/or metastasis, thereby leading to poor survival." (PMID 26867973, 2016). "Thus, the goal of this study was to assess tumor response and survival in patients with sensitized EGFR mutation-positive adenocarcinoma patients treated with EGFR-TKIs using uni-dimensional and volumetric methods." (PMID 26984681, 2016). "The lower sensitivity for KRAS mutation as compared with EGFR mutations could be due to the different tumor load." (PMID 27448974, 2016). "In addition, we demonstrate that EGFR amplification is most prevalent in proximally located tumours and significantly associated with decreased survival, as defined by TTR and CSS." (PMID 27387915, 2016). "The cytologic tumor marker c-CYFRA was positively associated with EGFR mutations in NSCLC." (PMID 26979333, 2016). "EGFR mutation-induced cell proliferation causes changes in tumor biology and tumor metabolism, which may reflect tumor marker concentration and 18F-FDG uptake on PET/CT." (PMID 26979333, 2016). "Currently, advanced NSCLC patients are candidates to first-line therapy with EGFR TKIs such as gefitinib and erlotinib if their tumors bear activating mutations of EGFR that have been recognized as the major determinant of effective tumor response to these targeted agents." (PMID 27726115, 2016). "Five patients had an activating mutation of EGFR in both the primary tumor and the metastasis." (PMID 26968843, 2016). "The ALK translocation with different genes defined the second biggest group of so called oncogene-addicted tumours after EGFR mutated ones, but this evidence happened with the discovery of activity in vitro cell lines and in vivo mouse models of ALK inhibitors." (PMID 27433281, 2016). "Moreover, several studies demonstrate that EGFR expression correlates with the reduced disease-free and overall survival, poor prognosis, increased risk of disease recurrence, advanced tumor stage, and increased risk of metastasis." (PMID 26918608, 2016). "This synergistic effect was less obvious in EGFR mutated tumor models that may be due to endogenous AMPK activity and solely EGFR TKI (Tyrosine Kinase Inhibitor) sensitivity." (PMID 27279498, 2016). "Given that tumor cells harboring a T790M mutation are still addicted to the EGFR signaling pathway, new drugs that irreversibly block EGFR, e.g., second-generation TKIs, may be capable of increasing the potency of EGFR-TK inhibition." (PMID 27455248, 2016). "In addition, the alternative transcripts encoding for the aberrant forms of EGFR were described both in tumor cell lines as well as in normal tissues." (PMID 27104520, 2016). "Moreover, the concomitant expression of AREG and EGFR was associated with enhanced tumor aggressiveness and shorter survival periods following tumor resection in PDAC." (PMID 27391842, 2016). "However, detection of EGFR mutations in NSCLC patients using sampling tumor tissues has significant limitations including tumor heterogeneity and difficulty in obtaining samples." (PMID 26755650, 2016). "Some patients with EGFR mutations may have been mistaken for patients with wild-type EGFR because of tumor heterogeneity." (PMID 27472739, 2016). "Western blot analysis of tumor lysates (derived from L3.6pL cells as xenografts) also showed that the loss of Sp TFs resulted in decreased expression of Sp-regulated gene products, survivin, bcl-2 and EGFR and also decreased expression of Sp TFs." (PMID 26967243, 2016).
tumor (continued). "Finally, vigorous tumor progression is paralleled by the occurrence of vast numbers of mutant alleles in the plasma (EGFR mutations in patients 2, 11, 13, and 14, as well as, KRAS mutations in patient 12)." (PMID 27640882, 2016). "In this cohort of patients, the effect of EGFR mutation on tumor metastases is site specific." (PMID 27486770, 2016). "Notably, NSCLC is a cancer for which genotyping of tumor cells, particularly with respect to epidermal growth factor receptor (EGFR) mutations, has demonstrated a remarkable level of success in treatment planning and efficacy." (PMID 27813497, 2016). "We additionally evaluated a prognostic impact of mPAP element for EGFR-mutated LADCs, as we considered an absolute volume of mPAP element may be more closely correlated with the malignant potential of the tumor than mPAP proportion." (PMID 27861549, 2016). "We have also demonstrated that EGFR GCN can be easily analysed by silver in situ hybridisation in diagnostic tumour material and thus could be applied as a routine histopathological diagnostic method." (PMID 27387915, 2016). "Thus, with no other evidence of shared mutations, the data suggest that patient 6 likely had three primary tumours carrying independent EGFR p.L858R mutations." (PMID 27767028, 2016). "Importantly, the EGFR-ErbB3 interdependency has been observed not only in tumor cells harbouring mutationally activated EGFR, but also in tumors with wild-type EGFR, revealing a role for ErbB3 that extends beyond the context of mutationally activated EGFR." (PMID 26862736, 2016). "However, analysis of plasma samples with NGS identified two EGFR mutations in patients with EGFR wild type tumor tissue (cases L29 and L33)." (PMID 27448974, 2016). "EGFR overexpression has been shown to be associated with high tumor grade, metastasis, poor prognosis, metaplastic morphology and secondary bladder recurrence in UTUC, and tumors with metaplastic features have been shown to react poorly to systemic chemotherapy." (PMID 27870887, 2016). "We prospectively collected tumor aspirates of 61 patients who underwent EGFR mutation analysis." (PMID 26979333, 2016). "When tumor proportion was below 5%, the EGFR mutation was detected less than half as often." (PMID 26992209, 2016). "The present study was a pre-planned exploratory analysis of a randomized phase III trial comparing erlotinib with gefitinib treatment in advanced NSCLC patients containing EGFR mutations in tumor tissues (The Chinese Thoracic Oncology Group 0901, CTONG0901, NCT01024413)." (PMID 27619632, 2016). "Factors that may predict beneficial effects from maintenance therapy include tumor histology, PS, and epidermal growth factor receptor (EGFR) mutation status." (PMID 27781159, 2016). "KRAS mutations were present in only 4% of the tumours and all tumours were EGFR wild-type." (PMID 26844548, 2016). "As for the correlations with positive cell infiltration, we observed that higher levels (above the median) of CD4+ cells in the tumor stroma correlated with epidermal growth factor receptor (EGFR)-mutated patients (p = 0.047) and with ADC histology (p = 0.030)." (PMID 27463005, 2016). "Therefore, the expanded RAS mutation analysis needs to be known before anti-EGFR treatment in mCRC, performed on tumor DNA from any location, as long as the performing lab complies with nationally or internationally qualified quality assurance programs (I, A)." (PMID 26669312, 2015).